S100B (S100 calcium binding protein B)
Diseases named in the same sentence as S100B in open-access papers (continued):
Sharing a sentence is not in itself a finding about the gene and the disease.
Stroke (continued). "Data from six longitudinal studies has demonstrated that, although serum levels of S100B are not raised immediately following acute ischemic stroke, a spike of serum S100B levels occurs 3 days after symptom onset of stroke." (PMID 37342100, 2023). "S100B is usually not detected in serum, increases only under stroke, subarachnoid hemorrhage, and cardiopulmonary bypass, and is thermostable." (PMID 36753509, 2023). "In that study, the mean S100B concentration 24 h after surgery was similar between the stroke and non-stroke groups (0.31 μg/l vs. 0.29 μg/l (p = 0.141))." (PMID 36747206, 2023). "The glial protein S100b can be produced by several peripheral cell subtypes including T-lymphocytes and it is not a specific indicator for stroke, as its levels are increased also in other neurological conditions." (PMID 36756347, 2022). "There is evidence that peripheral S100β level gives an estimation of extent of brain damage generally, not specifically for stroke, as its levels are increased also with other neurological conditions." (PMID 35813155, 2022). "Serum GFAP was not significantly different between groups, whereas S100B was significantly higher in stroke patients." (PMID 33115334, 2021). "However, in our study, when comparing NFL with NSE and S100β, NFL was the only marker that predicted stroke accurately at 12 h after surgery, with a better accuracy at 24 h than other biomarkers." (PMID 34859071, 2021). "Hill and colleagues reported a specificity of more than 95% for S100B measured on the first day of admission in 28 non-consecutive stroke patients but the measurement had poor sensitivity." (PMID 33633673, 2021). "Although the average S100β level of stroke patients was higher in patients who had a stroke than in patients who did not have a stroke at all study time points, the difference was not significant (all P > 0.05)." (PMID 34859071, 2021). "S100B and NSE were elevated in stroke and correlated with selected functional outcomes at 60 days." (PMID 33115334, 2021). "S100B, caspase-3 and NSE only distinguished IS from stroke mimics." (PMID 33633673, 2021). "Quantitative analysis showed that the number of S100β+ cells was not significantly different between the models at 1 d post stroke, suggesting that early reperfusion did not rescue astrocytes in peri-ischemic areas." (PMID 32492968, 2020). "Similar to the MAP2+ findings, early reperfusion following 90-min t-MCAO did not affect S100β+ astrocyte survival at 1 d post stroke." (PMID 32492968, 2020). "Compared to controls, stroke patients had significantly higher VEGF-A and VCAM-1 at <8 h that remained elevated at 72 h, with significantly higher VEGF-A at <8 h; ICAM-1 was significantly increased at <8 h, while S100B and E-selectin were unchanged." (PMID 32595585, 2020). "Our ongoing study (not yet published) on 600 stroke patients in Singapore showed that NT-proBNP and S100β were the best predictors for cardioembolic stroke (out of 30 different biomarkers)." (PMID 31163612, 2019). "In line with previous studies, we observed here that the attenuation of reactive gliosis influenced neither microglia/macrophage reactivity nor number and coverage of S100β astrocytes around the stroke lesion and the graft." (PMID 29401502, 2018). "The S-100β and NSE proteins cannot be detected in the serum under normal circumstances; however, they can be detected in serum following traumatic cerebral injury, stroke and cardiopulmonary bypass surgery due to impairment of blood–brain barrier (BBB)." (PMID 26179379, 2015). "The clinical performance of S100β protein therefore does not appear to be robust enough to differentiate ischaemic stroke, haemorrhagic stroke and stroke mimics." (PMID 25029344, 2014). "They reported that patients who suffered from stroke which was completely reversible within a few days had no increased serum S100B levels." (PMID 23509668, 2013).
Stroke (continued). "Several biomarkers such as S100β, glial fibrillary acidic protein (GFAP), matrix metalloproteinase-9 (MMP-9), and neuron-specific enolase (NSE) have been extensively studied in stroke." (PMID 23028472, 2012). "Elevated S100B levels may not directly predict an imminent stroke event; however, it may serve as a marker of neurological damage that has occurred, reflecting the severity of the event." (PMID 41296388, 2025). "To investigate stroke‐induced changes in pan‐lactylation across different brain cell types, we performed immunofluorescence co‐staining of pan‐Kla with markers of neurons (MAP2 or NeuN), astrocytes (GFAP or S100β), microglia (IBA1), and oligodendrocytes (Olig2 or MBP)." (PMID 40271828, 2025). "In addition, the distribution of infarct volume according to S100β levels was similar between patients with dominant and non-dominant hemisphere stroke." (PMID 39358745, 2024). "Our results, together with previous results, suggest that serum S100β level may be an important marker to assist in determining stroke severity regardless of infarct location." (PMID 39358745, 2024). "Similarly, GFAP, S100b and NSE, among others, have been investigated as the biomarkers for stroke." (PMID 38649772, 2024). "The conducted analyses revealed that the S100B level after 72 h and the change in the levels between the measurement points are the optimal prognostic factors for the adverse outcome irrespective of the stroke type." (PMID 38248781, 2024). "Indeed, a few studies in IS patients demonstrated a correlation between infarct size, but not stroke severity and levels of serum S100B on the 3rd day after stroke." (PMID 34685473, 2021). "S100b, like NSE, could reflect brain damage in post-cardiac arrest and stroke." (PMID 33566872, 2021). "We evaluated whether copeptin and S100b protein (PS100b) assessment, alone or in combination, could rule out stroke in patients visiting EDs for dizziness." (PMID 31387626, 2019). "Interestingly, aside from S100β, which is a marker of astrocyte activation, the biomarkers in this stroke panel are not specific to central nervous system tissues." (PMID 27247610, 2016). "The Triage Stroke Panel is a rapid, point-of-care fluorescence immunoassay to be used with the Triage MeterPlus for the rapid, quantitative measurement of BNP, fibrin degradation products containing D-dimer, MMP-9 and S-100β in EDTA-anticoagulated whole blood or plasma specimens." (PMID 27247610, 2016). "In addition, elevated S100B concentrations are not specific to ischaemic brain injury and the pattern of change in S100B levels is variable depending on the stroke subtype." (PMID 21034449, 2010). "While S100B may not serve as a reliable biomarker for diagnosing AIS, its potential utility lies in identifying patients at increased risk of early neurological complications post-stroke and predicting functional outcomes." (PMID 39459548, 2024). "While S100B is not considered a valuable biomarker for diagnosing AIS, it may serve a more useful role as an additional tool for identifying patients at increased risk of specific early neurological complications after a stroke." (PMID 39459548, 2024). "However, the involvement of S100b in stroke has not yet been fully investigated." (PMID 36756347, 2022). "But severe stroke does not obligatorily mean large infarction, as reflected by S100B peak levels, since a small infarction in the brainstem or internal capsule is related to a severe deficit, whereas a major infarction in the temporal and occipital lobe may be associated with only a mild deficit." (PMID 25613713, 2015). "The increased concentrations of GFAP and S100B in serum are more significant for patients with symptomatic stenosis (two patients had TIA, two patients had stroke, and one patient died) after CAS than the patients without complications." (PMID 34381130, 2021).
Stroke (continued). "We found that the AUC of S100-β combined with END at 48 h of stroke onset (model A) was not significantly different from the AUC of END (P = 0.379), but that S100-β combined with NHISS score (model B) statistically significantly increased the AUC of NHISS score to 0.735 (P = 0.016)." (PMID 39669377, 2024). "Furthermore, for these patients who had the neurological deficits (two patients with stroke and one patient who died), the serum concentrations of GFAP and S100B still could not return to the baseline level even at the 30-day follow-up." (PMID 34381130, 2021).
Alzheimer disease (84 papers, 2007 to 2025). A progressive, neurodegenerative disease characterized by loss of function and death of nerve cells in several areas of the brain leading to loss of cognitive function such as memory and language. "Concurrently, high expression levels of S100B are involved in neuroinflammation and have been notably associated with neurodegenerative disorders such as Alzheimer's disease and Parkinson's disease." (PMID 38274881, 2023). "We then use genetic instruments identified for S100β to test for bidirectional causal associations with Alzheimer’s disease, via two-sample Mendelian randomisation." (PMID 35028426, 2021). "Bidirectional, two-sample Mendelian randomisation was used to test for causal associations between S100β and Alzheimer’s disease." (PMID 35028426, 2021). "This will further elucidate the likelihood of a causal relationship between S100β and Alzheimer’s disease." (PMID 35028426, 2021). "Two-sample Mendelian randomisation (MR) was used to test for a causal association between S100β serum levels (using ourcis GWAS data) and Alzheimer’s disease." (PMID 35028426, 2021). "To examine the role of S100B in genetic susceptibility to Alzheimer’s disease (AD), we conducted a case-control study to analyze four polymorphism loci (rs2839364, rs1051169, rs2300403, and rs9722) of the S100B gene and AD risk." (PMID 33982673, 2021). "Studies have shown that S100B is associated with cognitive function in many diseases, such as Alzheimer's disease(AD), cerebral vascular disease, schizophrenia and mood disorders." (PMID 32112645, 2020). "S100B levels are elevated in the brains of patients with Alzheimer's disease or Down's syndrome, and the protein is implicated in cancer." (PMID 21445240, 2011). "Increased S100B levels are associated with a variety of neurological disorders including Alzheimer's disease (AD), multiple sclerosis, amyotrophic lateral sclerosis, schizophrenia, epilepsy, alcoholism, drug abuse, hypoxia and traumatic brain injury." (PMID 21080947, 2010). "In this regard, association between elevated brain levels of S100B and several brain pathologies including Alzheimer disease is a well-established notion." (PMID 20827421, 2010). "Oxytocin, a neuropeptide involved in social bonding and stress regulation, has been shown to exert neuroprotective effects, while S100B, a calcium‐binding protein, has been linked to neuroinflammation and neurodegenerative disorders, such as Alzheimer's disease." (PMID 40487975, 2025). "In the central nervous system (CNS), S100B promotes proliferation and inhibits differentiation of astrocytes, and increases in S100B are associated with neural diseases such as amyotrophic lateral sclerosis, multiple sclerosis, depression, Alzheimer's disease, and schizophrenia." (PMID 25536222, 2014). "Moreover, S100β has been linked to different brain pathological conditions such as Alzheimer's disease and Down's syndrome." (PMID 22135676, 2011). "The increased levels of S100B in Alzheimer's disease may also be associated with a loss of serotonin." (PMID 20827311, 2010). "Moreover, high levels of S100B cause GSK3β-dependent hyperphosphorylation of τ protein (a hallmark of Alzheimer disease) via RAGE-dependent activation of JNK and upregulation of Dickopff-1, a stimulator of GSK3β activity, in human neural stem cells." (PMID 20827421, 2010). "Data have been reported, indicating S100B as a key molecule in pathogenic processes and S100B levels in biological fluids as a reliable biomarker in a series of neural disorders, including acute brain injury, Alzheimer’s disease, Parkinson’s disease, or amyotrophic lateral sclerosis." (PMID 34948360, 2021). "Currently, both tau isoforms and GFAP are used in the prediction and diagnosis of neurodegenerative diseases, particularly Alzheimer disease, and S100B in mild traumatic brain injury guidelines." (PMID 40523276, 2025).
Alzheimer disease (continued). "In fact, increased S100β expression is seen in many neuropathologies including Alzheimer’s disease, Parkinson’s disease, cerebral ischemia, and traumatic brain injury." (PMID 40843691, 2025). "The presence of S100B in cerebrospinal fluid (CSF) indicates the early symptoms of Alzheimer’s dementia which is one of the crucial adverse events for delirious patients." (PMID 39700095, 2024). "In a transgenic mouse model of Alzheimer’s disease, overexpression of S100B resulted in increased Aβ deposits, enhanced astrocytosis and microgliosis, and higher levels of pro-inflammatory cytokines, when compared to control mice." (PMID 39766257, 2024). "Of note, increased expression of S100B, S100A4, S100A6, S100A8, and S100A9 has also been linked with Alzheimer's disease." (PMID 38737767, 2024). "Cryptotanshinone (CPT) has shown anti-inflammatory and neuroprotective effects in mouse models of Alzheimer's disease (AD) by significantly reducing the expression of S100β, GFAP, COX-2, iNOS, and NFkBp6530." (PMID 38796623, 2024). "Similar to serum S100B, CSF S100B is elevated in frontotemporal lobe dementia and earlier stages of Alzheimer’s disease." (PMID 37474905, 2023). "In transgenic mice, higher serum S100B levels were related to brain-region-specific and sex-dependent amyloid-β deposition, suggesting a role of S100B in the pathophysiology of Alzheimer’s disease." (PMID 36771418, 2023). "Mendelian Randomization summary statistics for two-sample, bidirectional tests between S100β serum levels and Alzheimer's disease." (PMID 35028426, 2021). "It was also described that overexpression of human S100β exacerbates cerebral amyloidosis and gliosis in the mouse model of Alzheimer’s disease." (PMID 34209847, 2021). "Altogether, these findings unveil features relevant in the definition of selectivity of the S100B chaperone, with implications in Alzheimer’s disease." (PMID 33807304, 2021). "Increased CSF S100B levels have also been found in in Alzheimer’s disease, frontotemporal dementia or brain injury." (PMID 32792937, 2020). "The predictive role of S100B in a variety of neurodegenerative diseases such as Alzheimer’s disease, has been shown to be closely related to cognitive function." (PMID 32112645, 2020). "RAGE mediates also the phagocytic profile of astrocytes and the interaction with other ligands, including S100β, involved in Alzheimer disease neuroinflammation." (PMID 31611796, 2019). "In contrast, in the brain of APP23 mice, a mouse model for Alzheimer’s disease, S100B, S100A6, and S100A8 show co-localization with Aβ plaques, compatible with astrocyte activation, and the expression level of S100A8 is increased in neural cells." (PMID 31281238, 2019). "One such protein is neuronal S100B, a calcium and zinc binding damage-associated molecular pattern (DAMP), whose chronic upregulation is associated with aging, Alzheimer’s disease (AD), motor neuron disease and traumatic brain injury (TBI)." (PMID 29386995, 2017). "Increased S100B cerebrospinal fluid levels were also reported in Parkinson's disease, Alzheimer's disease, and schizophrenia, implying roles for S100B in the pathogenesis of neurodegenerative diseases." (PMID 27242430, 2016). "Elevated S100B levels have been detected in brains of patients with Alzheimer disease, Creutzfeld-Jacobs disease, schizophrenia, brain tumors and epilepsy." (PMID 27159591, 2016). "It should be noted that altered levels of S100B have been found in other neuropsychiatric disorders such as schizophrenia, autism, and Alzheimer’s disease, implicating that alterations in levels of this molecule are not specific for major depression." (PMID 26364276, 2015). "Among the different signaling molecules released during reactive gliosis occurring in Alzheimer's disease (AD), the astrocyte-derived S100B protein plays a key role in neuroinflammation, one of the hallmarks of the disease." (PMID 26295040, 2015).